C12orf42 (chromosome 12 open reading frame 42)
Synonyms: FLJ25323
Tractability: No criterion of Open Targets' tractability assessment is met for any kind of drug.
Gene: Protein-coding gene on chromosome 12 (103,237,591 to 103,495,978, reverse strand). Ensembl gene ENSG00000179088.
Genetic constraint (gnomAD): Loss-of-function variants: 22 observed, 17.19 expected, observed/expected ratio (o/e) 1.28, 90% interval 0.91 to 1.78. The upper end of that interval is the gene's LOEUF score, 1.78, which puts it in group 6 of 6, group 1 being the genes least tolerant of losing a copy. Missense variants: 399 observed, 395.38 expected, observed/expected ratio (o/e) 1.01, 90% interval 0.93 to 1.1. Synonymous variants: 149 observed, 157.76 expected, observed/expected ratio (o/e) 0.94, 90% interval 0.83 to 1.08.
Homologues: Orthologues: chimpanzee C12H12orf42 (99% identical), macaque C11H12orf42 (89% identical), rabbit C12orf42 (60% identical), rat C7h12orf42 (42% identical), mouse 1700113H08Rik (41% identical).
Diseases named in the same sentence as C12orf42 in open-access papers:
C12orf42 is named in the same sentence as 6 diseases in open-access papers, as found by Europe PMC text mining. Sharing a sentence is not in itself a finding about the gene and the disease. The quoted sentences say what the papers report.
pulmonary arterial hypertension (2 papers, 2025). Pulmonary arterial hypertension (PAH) is a group of diseases characterized by mean pulmonary artery pressure >20 mmHg and elevated pulmonary arterial resistance leading to right heart failure. "Other genes in the signature, such as Chromosome 12 Open Reading Frame 42 (C12orf42) and phosphatidylinositol glycan anchor biosynthesis, class L (PIGL), have been associated with pulmonary arterial hypertension, smoking initiation, and FVC." (PMID 40894069, 2025).
autoimmune hypothyroidism (1 paper, 2024). "A common genetic etiology was proposed between hypothyroidism and OLP81 and our study supports this, indicating variation at nine loci (IFIH1, LPP, CEP43, TNRC18, C12orf42, TNFSF11, ST3GAL6, IL2RA, and IKZF3) that are strongly associated with both LP and autoimmune hypothyroidism." (PMID 38776927, 2024). "Five of the most significant hits after HLA—TNFSF11, CEP43, LPP, C12orf42, and IFIH1—and ten overall coincide with the same direction of effect as seen in the FinnGen and/or UKBB autoimmune hypothyroidism GWAS." (PMID 38776927, 2024).
pancreatic cancer (1 paper, 2021). "The key findings of the current study highlights ZNF804A, ZFP82, TRIM58, SOX17, and C12orf42 as hypermethylated/downregulated genes in pancreatic cancer associated with the development and progression of pancreatic cancer through their modulation of specific pathways." (PMID 33833773, 2021). "Taken together, the key findings of the current study demonstrate that ZNF804A, ZFP82, TRIM58, SOX17, and C12orf42 are hypermethylated/downregulated genes in pancreatic cancer and may be associated, through their modulation of specific pathways, with unfavorable pancreatic cancer prognosis." (PMID 33833773, 2021). "Univariate Cox model and Kaplan–Meier method revealed that, among 31 MeDEGs, 5 hypermethylated/downregulated genes (ZNF804A, ZFP82, TRIM58, SOX17, and C12orf42) were correlated with poor survival of patients with pancreatic cancer." (PMID 33833773, 2021). "However, the role of C12orf42 in pancreatic cancer requires further experimental validation." (PMID 33833773, 2021). "In the current study, 5 hypermethylated/downregulated genes in pancreatic cancer were identified, including ZNF804A, ZFP82, TRIM58, SOX17, and C12orf42, all of which were found to be correlated with the poor survival of pancreatic cancer patients." (PMID 33833773, 2021).
tumor (1 paper, 2021). "Among which, the hypermethylation of ZNF804A, ZFP82, TRIM58, SOX17, and C12orf42 were all noted to be significantly associated with tumor-related pathways, including calcium signaling pathways, neuroactive ligand-receptor interaction, glycosynthetic ganglion series and intercellular junctions." (PMID 33833773, 2021).
C12orf42 also shares sentences with these, for which no sentence is quoted: Cirrhosis (1 paper); hypothyroidism (1).